RNU7-143P (RNA, U7 small nuclear 143 pseudogene)
Gene: Small nuclear RNA gene on chromosome 7 (23,450,658 to 23,450,722, forward strand). Ensembl gene ENSG00000252590.
Homologues: Orthologues: chimpanzee U7 (100% identical), macaque U7 (97% identical), pig U7 (82% identical). Paralogues in human: RNU7-35P (86% identical), RNU7-7P (86% identical), RNU7-52P (85% identical), RNU7-23P (83% identical), U7 (83% identical), RNU7-141P (82% identical), RNU7-14P (82% identical), RNU7-19P (82% identical), RNU7-24P (82% identical), RNU7-28P (82% identical), RNU7-3P (82% identical), RNU7-73P (82% identical), and 143 more.